TLR9 (toll like receptor 9)
Diseases named in the same sentence as TLR9 in open-access papers (continued):
Sharing a sentence is not in itself a finding about the gene and the disease.
malaria (continued). "TLR2, TLR4, TLR9, and downstream signaling pathways of these proteins have recently been implicated in human malaria pathogenesis." (PMID 19317913, 2009). "While one of the studies did not observe any clear association with severe malaria, another found TLR9 polymorphisms to be associated with the clinical manifestation of malaria during pregnancy." (PMID 19284650, 2009). "This study explores the contribution of TLR9 genetic variants to severe malaria using two approaches." (PMID 19284650, 2009). "The identification of these functional genetic variants will be crucial to attest any involvement of TLR9 in severe malaria." (PMID 19284650, 2009). "Despite these limitations, our findings indicate that variants of TLR4 and TLR9 may be molecular markers for the clinical presentation of malaria caused by P. vivax in the admixed population of the Brazilian Amazon." (PMID 40963451, 2025). "Longitudinal studies on populations with diverse malaria exposure and carrying the TLR9-1237T/C polymorphism may also reveal the risk of recurrent parasitemia and anemia, and the durability of specific IgG responses." (PMID 40587574, 2025). "In addition to intracellular TLR9 being responsible for the recognition of bacterial and viral molecular patterns, TLR9 was also associated with the recognition of malaria, an intracellular parasite." (PMID 38397178, 2024). "The mechanism of fever, as associated with malaria infection, is not well understood; however, a recent study in mice suggests that malaria-related fever is caused by stimulation of TLR9 by malarial DNA through hemozoin, an insoluble haemoglobin digestion product." (PMID 30894794, 2019). "Although the role of TLR2 and TLR4 in malaria remain unclear, mice deficient in TLR9 were reported to be resistant to PbA-induced experimental cerebral malaria (ECM), suggesting a pathological role of TLR9 rather than a protective role during cerebral malaria." (PMID 29495555, 2018). "TLR5 R392StopCodon and TLR9 -1486C/T may predispose individuals to P. vivax malaria, while TLR9 -1237C/T was associated with Pv-malaria with high parasitemia." (PMID 28850598, 2017). "Moreover, several investigators have studied the role of TLR9 genetic polymorphisms in major infection diseases, systemic lupus, type 2 diabetes and coronary artery disease, and malaria." (PMID 23766695, 2013). "Although TLR9 promoter polymorphisms have been associated with asthma, Crohn’s disease, clinical manifestation of malaria during pregnancy and high parasitaemia in a cohort of patients with uncomplicated malaria, no clear associations have been observed with severe malaria." (PMID 24312262, 2013). "Our data demonstrate the first evidence that polymorphisms inIL17 may be associated with uncomplicated malaria in the Cameroonian population while SNPs in, IL10 IL17RD, IRF1, TLR1 and TLR9 may be linked with severe malaria." (PMID 24312262, 2013). "TLR9 haplotypes analyses showed that TTAG haplotype was significantly associated with reduced relative risk of 0.2 for symptomatic malaria (P = 4×10-6) and a lower mean parasitaemia (0.007), while CTGA haplotype had an increased relative risk of 3.3 (P = 0.005)." (PMID 22594374, 2012). "It has been reported that TLR9 responds to haemozoin and parasite protein-DNA complex released from the parasitized erythrocytes, and TLR9 polymorphisms are associated with disease manifestation in malaria." (PMID 22348301, 2012). "In this study, the effect of TLR9 gene polymorphisms on symptomatic malaria was investigated and TLR9 polymorphisms and haplotypes were significantly associated with susceptibility to symptomatic malaria among Ghanaian children." (PMID 22594374, 2012). "Four TLR9 single nucleotide polymorphisms (SNPs) namely: rs187084 (C-1486 T), rs5743836(C-1237 T), rs352139 (G + 1174A) and rs352140 (G + 2848A) were genotyped by direct sequencing, and their attributable and relative risks for symptomatic malaria determined." (PMID 22594374, 2012).
malaria (continued). "However, the effect of TLR9 polymorphisms on mild malaria among the African population is not well understood." (PMID 22594374, 2012). "TLR9 T1237C rs5743836CC was associated with an increased risk of developing malaria (p = 0.03), although it was found with the same frequency in uncomplicated and severe malaria cases." (PMID 22691414, 2012). "Stimulation with polyinosinic-polycytidylic acid (TLR3), LPS (TLR4), and/or CpG oligonucleotide type A (TLR9) has been associated with altered cytokine production in whole cord blood or cord blood mononuclear cells isolated from infants born to mothers exposed to malaria in pregnancy." (PMID 30454004, 2018). "A human study analyzing the (rs187084, −1486C>T) polymorphism in the promoter region of TLR9 gene showed an increased risk of low birth weight among infants from pregnant women with malaria, whereas increased parasitemia was observed in adults with mild malaria." (PMID 23316245, 2012). "Smaller population studies in Brazil, Iran, and Ghana showed associations between these polymorphisms and mild clinical malaria in their respective populations, raising the possibility that the TLR9 gene polymorphisms might be associated with a milder form of the disease." (PMID 23316245, 2012). "This study aimed to evaluate the association between polymorphisms in TLR1, TLR4, TLR7, TLR8, TLR9 and TIRAP and the clinical manifestations of malaria caused by P. vivax in a population from the Amazon region of Pará, Brazil." (PMID 40963451, 2025). "Our findings suggest that people with a specific genetic variation, known as a heterozygous genotype in the TLR9 gene, had different levels of antibodies against two malaria proteins." (PMID 40587574, 2025). "Elevated levels of anti–PS IgG observed in malaria are produced by Tbet+ atypical memory B cell (atMBC) in response to IFN-γ and parasite DNA via TLR9, both of which are associated with malarial anemia." (PMID 38652559, 2024). "In the case of pregnancy malaria, primiparous infected mothers with common TLR4 and TLR9 polymorphic variants are correlated with severe complications such as low birth weight and maternal anemia." (PMID 33013876, 2020). "TLR4 and TLR9 are strongly activated by malaria parasite PAMPs such as glycosylphosphatidylinositol (GPI), DNA, and hemozoin." (PMID 33013876, 2020). "In malaria endemic populations, single nucleotide polymorphisms (SNPs) within the TLR4 coding and TLR9 promoter regions are associated with variation in disease severity and parasitemia control." (PMID 33013876, 2020). "Different polymorphisms in the TLR9 gene have been described and known to be associated with diseases like bacterial meningitis, CMV infection, toxoplasmosis, malaria and SLE." (PMID 30651082, 2019). "TLR7 and TLR9 have been reported to contribute to innate immune sensing during blood-stage infection in murine malaria models." (PMID 30972055, 2019). "In malaria, it is known that hemozoin as malaria pigment activates innate immune response through TLR9." (PMID 29902248, 2018). "Studies have reported that hemozoin is a carrier of malaria parasite DNA into endosomes for TLR9 recognition." (PMID 30619355, 2018). "Of all the SNPs studied, only TLR9 -1486C/T slightly deviated from the HWE in Pv-malaria cases (p = 0.006)." (PMID 28850598, 2017). "Another piece of information supporting the role of TLR signaling during malaria was derived from the finding, which has demonstrated the activation of regulatory T (Treg) cells in a TLR9-dependent manner." (PMID 28400771, 2017). "During malaria, TLR9 is involved in providing protective immune response in a MyD88-dependent manner." (PMID 28400771, 2017). "Fever (COEF = 7599.46, 95% CI = 3063.80–12135.12, p = 0.001) and the C/C genotype of TLR9 -1237C/T (COEF = 17006.63, 95% CI = 3472.83–30540.44, p = 0.014) were independently associated with increased parasitemia in patients with Pv-malaria." (PMID 28850598, 2017).
malaria (continued). "Carriers of the T allele were at higher risk for developing Pv-malaria (TLR5 OR = 2.1, [95% CI: 1.0–4.3, p = 0.034]; TLR9 OR = 1.3, [95% CI: 1.0–1.7, p = 0.02])." (PMID 28850598, 2017). "Circulating pDC in P. falciparum infected Fulani, an ethnic group less susceptible to symptomatic malaria, on the contrary, display a mature phenotype with upregulated CD86 and HLA-DR expression and strong TLR9 responsiveness." (PMID 28572564, 2017). "TLR9 was reported to play an important role in the regulation and development of protective immunity to malaria." (PMID 27716849, 2016). "Our results also points to an interesting notion that the expression of high levels of CD36 and selective expression of TLR9 by human pDCs is an evolutionary adaptation for the effective immune responses to malaria during the long course of their co-existence." (PMID 24204889, 2013). "Malaria parasites induce strong pro-inflammatory cytokine responses in both human and mouse DCs predominantly through TLR9-mediated recognition." (PMID 24204889, 2013). "Activation of TLR9 expressed on dendritic cells has also been proposed as a mechanism used by malaria parasites to trigger regulatory T-cells to evade the immune system." (PMID 24312262, 2013). "In the case of malaria, TLR9 has emerged as a major sensor of infection, although the identity of the ligand remains controversial." (PMID 23144737, 2012). "It was recently reported that malaria-induced priming of the TLR response was TLR9-, MyD88-, and IFN-γ-dependent." (PMID 22463100, 2012). "Activation of TLR9 by A-type CpG DNA leads to induction of IFNA in pDCs through a MYD88- and IRF7-dependent mechanism, and previous work similarly found TLR9-dependence of IFNA production in pDCs during in vitro infection with malaria parasites." (PMID 23144737, 2012). "This study was planned to make a further contribution to solving the problem of the real role of the most common polymorphisms of TLR4, TLR9, TIRAP and FCGR2A in modulating the risk of malaria and disease severity." (PMID 22691414, 2012). "TLR2 and TLR4 have been reported to recognize Plasmodium falciparum glycosylphosphatidylinositol (GPI), while TLR9 has been reported to recognize malaria haemozoin and/or Plasmodium DNA-bound haemozoin." (PMID 22594374, 2012). "TLR9 haplotypes were inferred using the PHASE software and analysed for the risk of symptomatic malaria." (PMID 22594374, 2012). "Hemozoin, a bio-crystalline substance, is a hemin detoxification by-product of malaria parasites, have been shown to mediate innate immune system activation through TLR9." (PMID 21931708, 2011). "The components of malaria parasite that activate DCs through the recognition of TLR9 have been controversial." (PMID 21687712, 2011). "For example, it is known that Plasmodium DNA bound to either malaria pigment or protein components, activates the TLR9 pathway and that P. falciparum glycosylphosphatidylinositol (GPI) activates TLR2." (PMID 21483827, 2011). "Although it is not known if these molecules can specifically stimulate proliferation upon binding to natural Treg cell–expressing TLRs, a recent study demonstrated that TLR9 engagement in DCs is required for natural Treg cell activation by malaria parasites." (PMID 20442856, 2010). "The aim of this study was to assess the contribution of genetic variation at TLR9 to severe malaria." (PMID 19284650, 2009). "Activation of TLR9 expressed on dendritic cell has also been proposed as a mechanism used by malaria parasites to trigger regulatory T cells and evade the immune system." (PMID 19284650, 2009). "This study focused on TLR2, TLR4, TLR9 and MAL because these genes have been implicated in human malaria pathogenesis." (PMID 19317913, 2009). "Cells of newborns of mothers with malaria pigment in their placenta also exhibited significantly increased cytokine responses upon TLR9 stimulation." (PMID 19889240, 2009).
malaria (continued). "Recently, rapid progression phenotype following HIV infection and malaria manifestation during pregnancy were both traced to TLR9 polymorphic positions." (PMID 19924287, 2009). "In malaria, TLR9 recognizes free or hemozoin-bound parasite DNA." (PMID 40587574, 2025). "Therefore, this study aimed to analyse the potential influence of variants of TLR1, TLR4, TLR7, TLR8, TLR9 and TIRAP on the clinical manifestations of malaria caused by P. vivax in the Amazon region of Brazil." (PMID 40963451, 2025). "Malaria-induced autoimmune anemia has recently been hypothesized to be due to a TLR9/IFN-γR (TLR9/IFN-gamma receptor) synergistic activation mechanism of T-bet+ (transcription factor T-bet+) B cells." (PMID 39273791, 2024). "Hemozoin is a malaria parasite byproduct, and a natural ligand of TLR9." (PMID 37639483, 2023). "As TLRs have been shown necessary in the process of priming for induction of pro-caspase-11 and TLR7 as well as TLR9 are strongly activated by infection with malaria parasites, we investigated the role of NAS-TLRs on activation of the noncanonical inflammasome pathway." (PMID 32929083, 2020). "TLR1, TLR2, TLR4, TLR6, TLR7 and TLR9 have been reported to recognize malaria ligands." (PMID 33344264, 2020). "Similarly, growing malaria parasites digest haemoglobin to produce inert haemozoin moieties, which are recognized by TLR9 by an unusual process where haemozoin forms a complex with the parasite DNA and is presented to TLR9." (PMID 32867164, 2020). "Subsequently, it was shown that the TLR9 signaling-inducing malaria factor is DNA." (PMID 30619355, 2018). "However, the clinical relevance of TLR-mediated immune responses in the susceptibility to malaria has been mainly reported for endosomal PRRs such as TLR3, TLR7/8, and TLR9 in African children." (PMID 30384846, 2018). "Since, TLR9 deficiency compromises host control of parasitemia, TACI deficiency may also be negating the beneficial effect mediated by malaria TLR9 agonists." (PMID 30473702, 2018). "Together, these data confirm recent studies with Pf-malaria and suggest that TLR9 may play a key role in controlling parasitemia." (PMID 28850598, 2017). "And amongst Ghanaians, susceptibility to mild malaria was correlated with TLR9 T1486C rs187084, but not with TLR9 G2848A rs352140." (PMID 25157202, 2014). "Our data demonstrate the first evidence that polymorphisms in IL17 may be associated with uncomplicated malaria in the Cameroonian population while SNPs in, IL10, IL17RD, IRF1, TLR1and TLR9 may be linked with severe malaria in general." (PMID 24312262, 2013). "The activation of dendritic cells by malaria schizonts has been demonstrated to involve TLR9." (PMID 24312262, 2013). "It has also been reported that P. falciparum haemozoin, a crystalline by-product of haemoglobin metabolism by malaria parasites, is recognized by TLR9 on macrophages, although more recently it has been suggested that instead haemozoin-bound nucleic acids are the true ligand for this receptor." (PMID 22463100, 2012). "TLR9 mediates innate immune activation by the malaria haemozoin and protein-DNA complex." (PMID 22873687, 2012). "Two studies, carried out in Brazil and Iran, reported no influence of TLR9 promoter polymorphism on susceptibility to mild malaria in their respective populations." (PMID 22594374, 2012). "Studies implicating TLR9 in recognition of malaria were conducted using in vitro-differentiated plasmacytoid dendritic cells (pDCs), suggesting that pDCs may play a role in in vivo recognition of Plasmodium infection." (PMID 23144737, 2012). "This study was planned to make a further contribution to solving the problem of the real role of the most common polymorphisms of TLR4, TLR9, TIRAP and FCGR2A genes in modulating the risk of malaria and disease severity in children from Burundi, Central Africa." (PMID 22691414, 2012).
malaria (continued). "TLR9 T1237C seems to condition susceptibility to malaria in Burundian children but not its severity, whereas none of the assessed SNPs of TLR4, TIRAP and FCGR2A seem to influence susceptibility to malaria and disease severity in this population." (PMID 22691414, 2012). "Initially, TLR9 was proposed as the binding receptor of hemozoin, this remains controversial as it has been later shown that TLR9 activation by hemozoin is mediated by malaria DNA attached to the crystal and that the activation of TLR9 by hemozoin was abolished upon treatment with nucleases." (PMID 22131998, 2012). "On haplotype analysis, the TLR9 TTAG (−1486 T, -1237 T, +1174A, +2848 G) haplotype, the most frequent haplotype (39.1%) in the study population, was significantly associated with protection against symptomatic malaria and high parasitaemia." (PMID 22594374, 2012). "Unfortunately, these data seem to differ from this hypothesis because TLR9 T1237C was more common in children with malaria than in uninfected controls but had the same frequency in ill children, independent of disease severity." (PMID 22691414, 2012). "Thus, collectively, these data demonstrated that parasite histone-DNA complex is the TLR9-dependent DC-activating constituent of malaria parasite nuclear material." (PMID 21687712, 2011). "When CpG, an immunostimulatory TLR9 agonist, was injected into human volunteers or injected with a malaria vaccine, it induced a transient neutropenia and injection site reactions that were linked to stimulation of the innate immune system and associated white blood cell sequestration." (PMID 22003411, 2011). "In general, the importance of TLRs in malaria is underlined by the fact that TLR4 polymorphisms can predispose to severe malaria and that polymorphisms in both TLR4 and TLR9 may play a role in the severity of pregnancy associated malaria." (PMID 21483827, 2011). "Although TLR9 activation by malaria parasites is well reported, the implication to the susceptibility to severe malaria is not clear." (PMID 19284650, 2009). "No convincing association was found with polymorphisms in TLR9 for malaria severity, in either Gambian or Malawian populations, using both case-control and family based study designs." (PMID 19284650, 2009). "It is also possible that there exist TLR9 regulatory variants that contribute to severe malaria resistance/susceptibility that have not been mapped." (PMID 19284650, 2009). "This study aimed to evaluate the frequency of SNPs in the TLR9 gene and their association with IgG antibody responses against PvCSP variants (VK247, VK210, and V-like) and PvMSP-119 among individuals presenting with symptomatic Plasmodium vivax infections in a malaria-endemic region of Venezuela." (PMID 40587574, 2025). "Specifically, we looked at how certain genetic variations in the TLR9 gene, which is part of the immune system, might affect the production of antibodies against malaria proteins in 210 Venezuelan individuals infected with Plasmodium vivax, one of the parasites that causes malaria." (PMID 40587574, 2025). "Specifically, the TLR9 1635A/G polymorphism (also referred to as 2848C/T in some studies) has been associated with thrombocytic thrombocytopenic purpura (TTP), meningococcal meningitis, cytomegalovirus infection in fetuses and newborns, symptomatic malaria and toxoplasmosis." (PMID 30651082, 2019). "In agreement with this, a Malian study of two ethnic groups with differing susceptibility to symptomatic malaria shows in P. falciparum infected malaria-susceptible Dogon, pDC downregulate HLA-DR expression, lack upregulation of CD86 and show impaired responsiveness to TLR9 stimulation." (PMID 28572564, 2017). "Furthermore, allelic expression imbalances have been observed, indicating that different individuals might differ in the expression of TLR9, which can lead to different responses to the stimulus induced by malaria motifs." (PMID 24312262, 2013).